CD14 (CD14 molecule)
Diseases named in the same sentence as CD14 in open-access papers (continued):
Sharing a sentence is not in itself a finding about the gene and the disease.
tumor (771 papers, 2003 to 2026). "In more detailed analyses utilizing multiplex immunohistochemistry, the micropapillary growth pattern was associated with decreased CD3+ T‐cell and CD14+HLA‐DR+ monocytic cell densities both in the tumor intraepithelial and stromal regions." (PMID 39917902, 2025). "We further show that MYXV can alleviate immune suppression by patient-derived ovarian tumor-associated CD14+ macrophages (TAMs) in coculture with tumor antigen-specific CD4+ T cells." (PMID 40872773, 2025). "CD14+/CD68+ tumor-associated macrophages are the predominant immune cells infiltrating osteosarcoma." (PMID 40136652, 2025). "CD14, typically involved in innate immune responses and predominantly expressed in myeloid-derived cells, is linked to immunosuppression and tumor invasiveness, with CD14+ exosomes promoting metastasis in cancer." (PMID 39594703, 2024). "For example, PVRL2 is highly expressed in CD14+ cells (as tumor-associated macrophages) and CD45- cells (as tumor cells) in breast, endometrial, ovarian, lung, and liver cancers." (PMID 39156900, 2024). "The largest population of immune cells was tumor-associated macrophages (70.5%) that co-expressed CD14, CD4, CD11c, CD64, and HLA-DR." (PMID 39682129, 2024). "Functionally, it was determined that SPP1+ macrophages exert an immunosuppressive role, while CD14+ monocytes were implicated in promoting tumor progression and angiogenesis." (PMID 38600248, 2024). "This is particularly plausible as CD14+HLA-DR low/− phenotypes are typically associated with therapy-resistant tumours, causing therapy discontinuation." (PMID 38804366, 2024). "While TAMs are well established as promoting tumor progression, a CD14+ DC subtype has also been previously linked to an immunosuppressive tumor microenvironment." (PMID 39211033, 2024). "In this study, we demonstrate that CD14− cDC2s can directly convert to CD1c+CD14+CD163+ DCs driven by tumor-associated factors." (PMID 38242119, 2024). "Collectively, immature CD14+ cDC2s are phenotypically plastic until they encounter tumor-associated factors that rigidify their plasticity." (PMID 38242119, 2024). "From these results, the authors proposed that high frequencies of CCL2+ tumor epithelial cells and CD14+ TAMs are significant risk factors for rapid tumor recurrence." (PMID 37208442, 2023). "These monocytic CD14+/HLA-DRlo/neg cells recently emerged as tumour-induced immunosuppression mediators and are associated with poorer CAR-T expansion during manufacturing." (PMID 36830882, 2023). "We found that BEST1 was mainly expressed on monocytes (CD14+) and tumor‐associated macrophages (TAMs) (CD68+) in the TME of HNSCC patients, and the positive ratio of BEST1 expression in cancer is significantly elevated than that in adjacent normal tissue." (PMID 37088729, 2023). "They then used flow cytometry to demonstrate that a portion of these FAP+CD45+ cells were CD11b+CD14+MHC−II + tumor associated macrophages." (PMID 38196606, 2023). "Increased CD14+ cell tumor infiltration was associated with a higher stage at diagnosis and more positive lymph nodes at the time of surgery." (PMID 36139660, 2022). "CD14 promotes inflammation and its expression on tumour-associated immune cells influences tumour immunosurveillance." (PMID 35203475, 2022). "A t-SNE dimensional reduction analysis then done on selected live Lin-CD45+CD14+MHCII+ macrophage subsets shows that skin-associated macrophages were enriched in the lower part of the t-SNE map contrary to tumor-associated ones." (PMID 36325333, 2022). "Tumor-promoting inflammation is another important hallmark of cancer that sodium selenite treatment reduced by downregulating CD14 and ZNF395 genes." (PMID 36059619, 2022). "Within the TME, CD14+ monocytes can infiltrate and differentiate into tumor-associated macrophages (TAMs) that can reach 40% of the tumor’s volume." (PMID 36387279, 2022).
tumor (continued). "All subsets expressed high levels of Cd11b, Csf1r, Csf2ra, Cd14, Cd64 and Cd68 confirming their initial classification as tumor-associated macrophages and monocytes." (PMID 34381732, 2021). "Flow cytometric TME analysis identified (tumor associated) CD14+CD163+ and CD14+CD204+ macrophages as critical determinants for PDX propagation." (PMID 34362423, 2021). "To provide myeloid cells with a tumor-associated phenotype we treated isolated CD14+ myeloid cells with tumor conditioned medium (TCM) derived from an established autologous tumor cell line." (PMID 34887574, 2021). "OLFML2B was highly co-expressed with tumor-associated macrophage markers such as CD14, CD163, CSF1R, ITGAM, and MRC1." (PMID 34868901, 2021). "In accordance with their immunosuppressive effect, high levels of CD14+HLA-DRlow monocytes are associated with significantly lower levels of tumor-specific T-cells in the circulation of cancer patients." (PMID 33042791, 2020). "Among the immune cells in the HCC tissue, tumor-associated macrophages (Mφ, TAMs) sustain tumor progression and are recruited from circulating CD14+ cells (monocytes) to the tumor microenvironment through tumor-derived signals." (PMID 32824016, 2020). "Consistent with previous reports, CD68, CD163, and CD14 antibodies strongly stained cells in the CHL tumor microenvironment in each of the variants." (PMID 31714922, 2019). "The upregulation of cytokine-encoding genes in whole AC tumor tissue was found to correlate to the presence of an immune infiltrate and the expression of inflammatory cell markers, like CD14 and CD68." (PMID 31191748, 2019). "Subsequently, DNA methylation-based deconvolution analysis using MethylCIBERSORT23 implicated CAFs, CD8 T cells and CD14 monocytes as directly correlated with C-ECM signature scores pan-cancer in addition to confirming inverse associations with tumour purity." (PMID 30410077, 2018). "The recruitment of CD14+ MDSCs was unexpected, since these cells are described to be mainly associated with immunosuppressive processes, such as tumor immune evasion and lymphocyte suppression through the production of reactive oxygen species." (PMID 29922280, 2018). "Within the perivascular niche, tumor associated macrophages (TAMs) were differentiated from microglia/macrophages, which resulted in a significant increase in CD14 expression in some regions and surrounding necrotic areas." (PMID 28771552, 2017). "Hypoxia is intimately involved in regulation of tumor-associated CD14+ cell function, immune suppression and tumor progression." (PMID 26343197, 2015). "A growing number of studies indicates the unique ability of tumor-associated IL-10 to convert even fully differentiated DC to CD14+ suppressive macrophage-like cells." (PMID 24324467, 2013). "At the same time, ALA increased the production of CD66b– CD14+ monocytes, while decreased the production of CD66b+CD14– neutrophils and CD66b+CD14+ proinflammatory monocytes or antigen-presenting cells (APCs)-like tumor associate neutrophil like cells derived from CD34+ HSPCs." (PMID 38589882, 2024). "CD14+HLA-DRlo/neg monocytes, as part of myeloid-derived suppressor cells (MDSCs), are implicated in tumor-induced immunosuppression and may modulate responses to immunotherapies." (PMID 39450166, 2024). "In addition, our study examined the possible characteristics of tumours that cause the invasion of CD14+APOE+ cells." (PMID 39187937, 2024). "Conversely, in the presence of high levels of IL-6 and PGE2, intratumoral cDC2s can also be driven toward a pro-tumor phenotype characterized by CD14 expression, upregulation of markers usually associated with tumor-associated macrophages (TAMs), and impaired antigen processing and presentation." (PMID 38903502, 2024). "Consequently, the high levels of cytokines secreted by CD14+ CD16- monocytes partly explain the tumor risks associated with these cells." (PMID 38533503, 2024).
tumor (continued). "To identify the extent of transcriptome remodeling in HCs from tumors (THC), we extracted the tumor fraction and compared the gene expression profile of THC with tumor epithelial cells (EPCAM+ and KRT8+) and THCs with tumor-associated macrophage/monocyte cells (CD14+ and CD163+)." (PMID 38611120, 2024). "Monoculture in tumor-conditioned medium (CM) caused a similar increase in the amount of CD1c+CD14+ cells (63% and 54%) as direct tumor-cell contact, whereas cDC2s cultured in medium led to 16% CD14+ cells." (PMID 38242119, 2024). "Moreover, inhibiting their signaling with anti-IL-6R and CSF1Ri kept CD14+ cDC2 frequencies equal to tumor-free conditions, underlining IL-6 and M-CSF as dominant drivers of tumor-induced CD14+ cDC2s." (PMID 38242119, 2024). "For CD14+ monocytes, there was also substantial upregulation of tumor-associated pathways." (PMID 38600248, 2024). "The panel consisted of primary antibodies against various immune cells, including CD20+ B cells, CD3+ T cells, CD8+ T cells, CD68+ macrophages (Mø), CD163+ tumor-associated macrophages (TAMs), CD14+ monocytes (M), CD15+ neutrophils (NE), FOXP3+ Treg cells, and the proliferation marker Ki67." (PMID 38164148, 2024). "In BrM specifically, the increased T cell infiltration is accompanied by a migration of CD14+CD206+ macrophages away from the perivascular regions into the tumor bed, which could cause the blood vessels to be more permeable to immune infiltrates." (PMID 37655659, 2023). "Importantly correlation analyses showed significant co-expression between CMKLR1 and genes specific of tumor associated macrophages (TAM) such as CD14, CD163, MRC1 and HLA-DRA in BC and MPM." (PMID 37539056, 2023). "Cluster 0 cells showed minimal transcriptional overlap with above known tumor-associated myeloid cells types, except overexpressing inflammatory response genes S100a8/9 and myeloid differentiating gene Cebpb, and pathogen recognizing gene Cd14." (PMID 37055410, 2023). "In addition, CD14+HLA-DRlow/− monocytes has been linked to tumor-induced immunosuppression, in association with unfavorable clinical outcomes as well as unresponsiveness to immunotherapeutic agents among cancer patients." (PMID 37337301, 2023). "Furthermore, several studies have demonstrated that endogenous DcR3 attenuates the Th1 response and skews the differentiation of tumor-associated macrophages, whereas DcR3–Fc modulates dendritic cell maturation from CD14+ monocytes." (PMID 34223817, 2021). "Moreover, treatment-induced tumor regression was associated with the restoration of antitumor activity in CD14+ cells." (PMID 32824016, 2020). "For CD14+HLA-DRlo/neg monocytes in particular, an extensive array of studies involving immunotherapy demonstrate that high baseline levels of these immunosuppressive monocytes were associated with diminished anti-tumor responses and/or poor clinical outcomes." (PMID 31191529, 2019). "We hypothesized that exosomes from PDAC cell lines would cause PMA-differentiated M0 macrophages that express CD14 to adopt an immunosuppressive phenotype that favors tumor cell invasion and metastatic spread." (PMID 30383833, 2018). "Similar to clinical scenarios, it was observed that myeloid cells infiltrated the tumor, numerous cells within the tumor expressed CD14 and CD163 which are commonly associated as macrophage markers, and CD163+ cells were most likely M2-like macrophages as they were HLA-DRlow and CD206high." (PMID 29411049, 2018). "As the interaction between tumor cells and monocytes appears to promote the loss of HLA-DR on monocytes, we hypothesized that CD14+ monocytes would likely be present in the tumor microenvironment." (PMID 26286851, 2015). "Indeed, the IL-10-conditioned CD14+ DDC with a DC-SIGN+BDCA3+CD163+ phenotype are highly reminiscent of both tumor-associated macrophages and DC, adopting similar M2-like immunosuppressive traits." (PMID 23875023, 2013).
tumor (continued). "Conversely, in the invasive margin, CD14+HLA-DR+ mature monocytic cells (p < 0.004 for all) were present at lower densities in the same tumour groups." (PMID 41454575, 2026). "Previous research has demonstrated that CCR2, by binding to its ligand CCL2, drives the migration of CD14+ CD16+ monocytes from the peripheral blood to tumor sites, constituting a key pathway for immune cell recruitment to the TME." (PMID 41497137, 2026). "RNAseq and cytokine profiling identified CD14 expression in tumor cells as a key upstream regulator of neutrophilic TME via NFκB signaling." (PMID 41486114, 2026). "Inhibiting CD14 expression in tumor cells reduces neutrophil-recruiting chemokines, leads to decreased neutrophil infiltration in the TME, and consequently lowers the risk of RT-promoted DM." (PMID 41486114, 2026). "In the tumour centre, CD14+HLA-DR- immature monocytic cells (p < 0.0002 for all) were more prevalent in tumours with high TSR, immature DR, and high SMAPS." (PMID 41454575, 2026). "As a future goal, we plan to generate CD14-knockdown cell lines and tumor models to further validate its mechanistic role." (PMID 41486114, 2026). "CD14 expression in tumor cells plays a pivotal role in shaping a neutrophil-enriched TME, which increases the susceptibility to RT-promoted DM." (PMID 41486114, 2026). "This function is critical for effective DC-based immunotherapies but is often hampered by tumor-derived immunosuppressive factors, as is observed for CD14+CD163+ tumor-induced DC3s (ti-DC3s)." (PMID 40789452, 2025). "Functionally, CD14+ DC3s are inferior tumor-antigen–specific CD8+ T cell activators compared to CD14− DC2s." (PMID 40789452, 2025). "CCL14 appears to be the primary recruiter of CCR1+CD14+ monocytes to the tumor mass, with high CCL14 levels correlating with poor prognosis." (PMID 40136652, 2025). "The HLA-DR+CD14+CD66b+ monocytes were significantly higher than in the non-tumor tissue (7.5 ± 1.8%) when compared with tumor tissue (21.1 ± 2.1%)." (PMID 40731885, 2025). "This study found that lobeline enhances the presence of CD14+ monocytes, DCs, and Dnajb1 high cells in the tumor microenvironment while reducing the number of Dnajb1 low cells." (PMID 39840525, 2025). "For example, a clone defined by 3068G>A mutation showed 35 CD14+ monocytes in the peripheral blood, 41 CD14 monocytes in the tissue, and 13 DCs in the tumor and NILT, likely reflecting continuous infiltration and differentiation." (PMID 40777278, 2025). "The HLA-DR+CD14+CD66b+ cells in tumor tissue were 3-fold higher and 10-fold higher when these cells were compared with the PB and non-tumor thyroid tissue." (PMID 40731885, 2025). "Regardless of CDK2AP1 status, CD68+ macrophages were mainly distributed in the periphery (P = .02), whereas CD3+ lymphocytes were primarily found infiltrating the tumor core (P = .009), as were monocytes (CD14+; P = .015)." (PMID 40112045, 2025). "Spatial maps showed that their TAM to MES2-like interactions (e.g., GRN-TNFRSF1A and CD14/ADAM9/ADAM17-ITGB1) were maximally enriched within high-CNV tumor-core domains and diminished toward infiltrative margins." (PMID 41235227, 2025). "Further in line with the immunosuppressive characteristics of tumor-induced CD14+ cDC2s is the increased expression of aldehyde dehydrogenase 1 family, member A2 (ALDH1A2)." (PMID 40789452, 2025). "Hyaluronan carried by tumor-derived microvesicles induces IL-10 production in classical (CD14++CD16−) monocytes via PI3K/Akt/mTOR-dependent signaling pathway." (PMID 40328660, 2025). "Alleviation of immunosuppression by CD14+ TAMs allows stronger CD4+ T cell responses to tumor antigen stimulation." (PMID 40872773, 2025). "More than 50% of MCs were colocalized with neighbouring cells of the tumour microenvironment within 20 μm, most frequently with monocytes (CD14+CD68+), M2 macrophages (CD68+CD163+), and endothelial cells (CD31+)." (PMID 40981193, 2025).
tumor (continued). "Mucinous differentiation was associated with higher densities of CD14+HLADR– immature monocytic cells and M2-like macrophages in mismatch repair (MMR) proficient tumours, and lower T-cell densities in MMR-deficient tumours." (PMID 39966658, 2025). "The tumor tissues exhibited increased immune cell infiltration and harbored CD66b-expressing neutrophil-like HLA-DR+CD14+ monocytic cells, which indicates an inflammatory milieu in malignant thyroid cancer." (PMID 40731885, 2025). "Studies have shown that CD8+CD14+ T-cells accumulate in liver allografts and during hepatic viral and tumor-specific responses in a mouse model, producing IL-10 and IL-2 ex vivo." (PMID 41148820, 2025). "CD14-positive cells localized to clusters 0, 3, 5, 6, and 14 and were classified as mutually exclusive TREM2 and FCN1 tumor-associated macrophages (TAMs), as previously reported." (PMID 41228323, 2025). "Similar cells have been shown to circulate as CD14+ monocytes in the blood of cancer patients, reside in mouse and human tumors, and increase tumor LVD and metastasis to LNs." (PMID 40507286, 2025). "The PWY.3001‐associated microbiota increases OS risk by inhibiting protective metabolites like cmpf (mediating effect of 35%), while F. plautii promotes tumor progression via CX3CR1 activation on CD14− CD16− protumor monocytes (mediating effect of 4.91%)." (PMID 41180320, 2025). "In this work, we analyzed changes in the proteome and secretome of human cDC2s during their tumor-induced conversion to CD14+ DC3s by quantitative whole-cell proteomics and THRONCAT." (PMID 40789452, 2025). "First, RO6870810 was associated with a suppressive effect on immune effector cells, evidenced by a decrease in CD14+/CD11b + monocytes and immune gene signatures in both the periphery and tumor." (PMID 40102759, 2025). "Future studies should aim to dissect the complex interactions between CD14 and other immune regulators, and how these interactions shape the tumor microenvironment." (PMID 40092684, 2025). "It is not surprising that these cathepsin-related functions so far only have been attributed to macrophages, given the phenotypic similarities between ti-DC3 and tumor-associated macrophages (e.g. CD163, CD14, CD11b expression)." (PMID 40789452, 2025). "CD56+ monocytes (CD14+CD56+) are capable of infiltrating the tumor, lysing tumor cells after activation with interferon (IFN) α, and stimulating cytotoxic functions of DCs." (PMID 41440002, 2025). "The proportions of antitumor immune cells (CD14+ monocytes, M1 macrophages, DCs, and CD8+ T cells) increased, but the tumor‐associated immune cells (M2‐like macrophages) decreased." (PMID 39840525, 2025). "To assess the impact of lidocaine on macrophage polarization within the tumor microenvironment, we evaluated the expression of CD163 and CD40 on CD14+ tumor-infiltrating immune cells (TIICs)." (PMID 40244064, 2025). "In relapsed tumor MC3Rb, malignant cells seemed to receive increased survival support from both CD14+ monocytes and myeloid cells through BAFF." (PMID 40876452, 2025). "Before the classification of DC3s, CD1c+CD14+ DCs were reported in various tumor contexts, also often referred as inflammatory DCs." (PMID 40584260, 2025). "In this work, we characterized the proteome and nascent secretome of DC2s during their tumor-induced conversion to immune incompetent CD14+ DC3s." (PMID 40789452, 2025). "Further investigation into CD14+ DC3s revealed that they can originate from CD14− DC2s, driven by tumor-secreted IL-6 and macrophage colony-stimulating factor (M-CSF), hence called tumor-induced CD14+ DC3s." (PMID 40789452, 2025). "Similar results were obtained with cDC2s stimulated with IL-6 + M-CSF (+PGE2), tumor-derived cytokines known to be responsible for the conversion of cDC2s to CD14+ DC3s." (PMID 40789452, 2025). "The extent of phagocytosis was quantified by measuring the percentage of CFSE+ tumor cells within CD14+ macrophages using flow cytometry." (PMID 40136470, 2025).